MIR1203 (microRNA 1203)
Synonyms: hsa-mir-1203; MIRN1203
Gene: MicroRNA gene on chromosome 17 (48,156,427 to 48,156,511, reverse strand). Ensembl gene ENSG00000221739.
Diseases named in the same sentence as MIR1203 in open-access papers:
MIR1203 is named in the same sentence as 1 disease in open-access papers, as found by Europe PMC text mining. Sharing a sentence is not in itself a finding about the gene and the disease.
MIR1203 shares sentences with these, for which no sentence is quoted: lung carcinoma (1 paper).